INS (insulin)
Diseases named in the same sentence as INS in open-access papers (continued):
Sharing a sentence is not in itself a finding about the gene and the disease.
thyroid disorders (52 papers, 2006 to 2026). "Taking medicines for cardiovascular, thyroid or rheumatic disease or gout or insulin use was associated with better adherence." (PMID 36691578, 2023). "It is possible that adiposity was associated with insulin resistance and increased production of insulin and insulin-like growth factors, which in turn was associated with thyroid disorders." (PMID 31619235, 2019). "Patients with known thyroid disorders or a history of thyroid ablative therapy, users of drugs that affect thyroid function, or fasting blood sugar and insulin were excluded." (PMID 38807716, 2024). "The altered glucose-insulin dynamics of hyperthyroid patients after the administration of anti-thyroid drugs are analyzed upon the proposed drug-treatment model." (PMID 36619543, 2022). "Patients of group 3 developed thyroid diseases on average only after the initiation of insulin treatment." (PMID 24580798, 2014). "Intriguingly, Pax8 modulates the expression of several genes involved in carcinogenesis and thyroid malignancies (phosphatidyl-inositol/insulin and MAPK pathways) and cell cycle processes (CDKN2BCCNB1 and CCNB2, among others)." (PMID 22531031, 2012). "Thyroid abnormalities (hyperthyroid and hypothyroid) are accompanied by changes in intermediary metabolism including alterations in body weight, insulin resistance and lipid profile." (PMID 16472384, 2006). "All three adipose tissue hormones and insulin correlated significantly with indices of thyroid function." (PMID 16472384, 2006). "We propose that changes in glucose and insulin levels here may be a secondary consequence of thyroid dysregulation." (PMID 34022907, 2021). "Our results also indicate that apart from its proven insulin sensitizing effect fenugreek might have a therapeutic potential in the adjuvant treatment of thyroid diseases." (PMID 31080828, 2019). "This trend of using insulin instead of metformin monotherapy was also observed in the majority of patients with HIV infection and thyroid disorders (17.58% vs. 10.31%, respectively)." (PMID 33240534, 2020). "Body Mass Index (BMI) over 25 kg/m2, or 35 kg/m2, chronic heart, liver, or renal failure, insulin treatment, uncontrolled T2DM, thyroid disorder, or treatment that can influence HRV parameters." (PMID 29608603, 2018). "Cabergoline administered to hyperprolactinemic women without thyroid pathology improved insulin sensitivity and plasma lipids, and reduced uric acid, hsCRP, fibrinogen, homocysteine, UACR, and FRS." (PMID 39852352, 2025). "Despite a neutral effect on BMI, fasting glucose, HbA1c, and blood pressure, cabergoline improved insulin sensitivity in both study groups, though this effect was stronger in women without thyroid pathology." (PMID 39852352, 2025). "Our findings show, for the first time, that a preserved skeletal MM within a framework of excess weight has a direct influence on thyroid function, in terms of a higher conversion of FT4 to FT3, independently of age, BMI, TSH, triglycerides, and insulin serum levels, but is affected by gender." (PMID 33117281, 2020). "Since thyroiditis and hypophysitis are often not appropriately diagnosed with the disease names in real-world practice, we defined endocrine abnormalities by using each replacement therapy (levothyroxine, hydrocortisone, and insulin) and the charge for T1DM in ICI-related T1DM." (PMID 40503677, 2025). "In the nonnodular thyroid group, thyroid volume was also positively related to serum insulin levels and HOMA-IR, whereas a negative correlation between thyroid volume and levels of leptin was identified in the nodular thyroid group." (PMID 28356911, 2017). "In the nonnodular thyroid group, thyroid volume was also positively related to serum insulin and HOMA-IR, whereas a negative correlation between thyroid volume and leptin was identified in the nodular thyroid group." (PMID 28356911, 2017).
cerebrovascular disease (51 papers, 2009 to 2025). "We examined associations of molecular markers of brain insulin signaling with cerebrovascular disease." (PMID 33858515, 2021). "However, there are only a few works devoted to the studies of the protective effect of insulin administered intranasally to animals with cerebrovascular disorders." (PMID 39057034, 2024). "First, IR activates inflammation-related genes and interferes with insulin signaling, leading to varying degrees of chronic inflammation, oxidative responses, and endothelial cell dysfunction to damage blood vessels, leading to cerebrovascular disease." (PMID 37386419, 2023). "Preoperative comorbidities included DM with insulin use in 2.8% of patients, preoperative respiratory distress within 30 d in 0.8%, COPD in 7.6%, and history of cardiac surgery and cerebrovascular disease in 0.6% and 3.0%, respectively." (PMID 35106414, 2022). "The results disclosing the ability of insulin to prevent autophagic death of brain neurons during brain ischemic and reperfusion injury or other cerebrovascular disorders are practically absent." (PMID 39057034, 2024).
peripheral vascular disease (51 papers, 2005 to 2025). Any disorder affecting blood flow through the veins or arteries outside of the heart. "The authors identified the associated factors: the frequency of insulin injections (<3 injections daily), alcohol abstinence, peripheral vascular disease, and retrieval of the reactive strips from the pharmacy." (PMID 37629520, 2023). "A seemingly interesting observation in patients with sickle cell anaemia (SCA) is that they usually have lower systemic blood pressures (BP) and insulin resistance than persons in the general population in spite of chronic inflammation and vasculopathy." (PMID 29468088, 2018). "The most common treatment is administration of exogenous insulin, but this neither cures T1D nor prevents its long-term complications including heart, kidney and peripheral vascular diseases." (PMID 32098630, 2020). "However, the influence of macrophages on the insulin sensitivity of other cells in PVAT and its implications for T2DM vasculopathy remain unclear." (PMID 39627688, 2024). "Foot insensitivity was more common in White Europeans than South Asians and more patients with foot insensitivity had history of peripheral vascular disease (PVD) and were prescribed insulin compared to those with normal monofilament test." (PMID 27876022, 2016).
essential hypertension (50 papers, 2007 to 2025). Hypertension that presents without an identifiable cause. "However, there are no studies revealing the link between prolonged activation of ECS in primary hypertension and insulin signaling pathway in cardiomyocytes." (PMID 32326330, 2020). "It is important to note that present study, which was based on a genetic model of primary hypertension (SHRs), has revealed the link between chronic activation of ECS by URB597 treatment (2-week) and insulin signaling pathway in cardiomyocytes subjected to the increased afterload." (PMID 32326330, 2020).
migraine (50 papers, 2012 to 2026). "The aim of this article is to provide an updated overview of the relationship between insulin and migraine, with both of them linked to inflammation, as well as to evaluate the potential therapeutic mechanisms of dietary interventions for migraine management." (PMID 40426647, 2025). "Insulin plays a role in the pathophysiological mechanism in migraine, as it is associated with glucose metabolism and directly affects the secretion of gonadotropins by the hypothalamus." (PMID 39247924, 2024). "Several studies have shown that disabled insulin sensitivity in migraines contributes to the possibility of increasing the risk of T2D for migraine patients." (PMID 35627115, 2022). "So far, at least 170 genetic variants (123 genomic loci) have been associated with migraine, 403 genetic variants (243 genomic loci) to T2D, 41 genetic variants to fasting glucose, and 17 genetic variants to fasting insulin." (PMID 35627115, 2022). "Additional migraine GWAS risk loci have been associated with fasting glucose and fasting insulin at (p < 0.05)." (PMID 35627115, 2022). "Several studies have found a close association between insulin resistance as well as associated elevated blood glucose, and insulin levels and migraine." (PMID 35889884, 2022). "Impaired glucose metabolism, reduced insulin sensitivity, and fluctuation of blood glucose levels have all been associated with the comorbidity of migraine and glucose-related traits." (PMID 35627115, 2022). "In this respect, hypoglycemia-regulated insulin in the hypothalamus has been associated with migraine." (PMID 34177788, 2021). "A similar restriction applies to studies on the association between DM and migraine, which lack data on drug use that not only influence weight, but also insulin sensitivity." (PMID 34177788, 2021). "Some genetic support for a potential role of insulin in migraine comes from associations between polymorphisms in insulin-related genes and migraine." (PMID 30974836, 2019). "In addition, early investigations supporting these results indicated metabolic alterations resulting from fasting or administration of glucose or insulin can lead to migraine attacks in susceptible patients." (PMID 35627115, 2022). "One may speculate as to whether insulin dysfunction may be a predisposing feature of metabolic abnormalities in migraine, or if it is a result of chronic CGRP exposure." (PMID 36175833, 2022). "Surprisingly, intravenous insulin infusion is effective in causing migraine aura." (PMID 35627115, 2022). "Therefore, higher plasma insulin levels in migraine patients can also be caused by CGRP, a neuropeptide expressed in sensory nerves associated with glucose metabolism and plays a vital role in migraine pathogenesis." (PMID 35627115, 2022). "Since the balance of glucagon/catecholamines and insulin controls lipolysis, insulin resistance is suggested to be associated with migraine pathophysiology may also account for the higher levels of UFAs in CM plasma." (PMID 34531722, 2021). "Subcutaneous fat, often in the gluteo-femoral region in women, appears to increase leptin and adiponectin levels, which may impair insulin sensitivity and modulation of inflammatory processes contributing to migraine risk." (PMID 23181051, 2012). "However, the molecular mechanisms underlying ADAMTS9’s effect on insulin action and migraine risk are currently unknown." (PMID 36808568, 2023). "Furthermore, insulin may be implicated in migraine pathophysiology because it is linked with glucose metabolism and directly impacts gonadotropin secretion through the hypothalamus." (PMID 35627115, 2022). "However, a modulation of the metabolic pathway linked to insulin metabolism might be of relevance in migraine prophylaxis." (PMID 33958992, 2021). "An observational study was conducted in 2005 to evaluate the effects of this dietary intervention on migraine in patients exhibiting altered glucose–insulin metabolism." (PMID 40426647, 2025).
migraine (continued). "ALA, a mitochondrial antioxidant, improves insulin sensitivity and reduces oxidative stress, addressing two critical aspects of migraine pathophysiology." (PMID 40426647, 2025). "The article will explore neurogenic inflammation in migraine, how insulin is involved in neurogenic inflammatory processes, what is known about insulin alterations in migraineurs, and finally, the potential impact of diet in modulating these processes." (PMID 40426647, 2025). "The relationship between dysregulated insulin metabolism and migraine involves several interconnected pathways: TRPV1 sensitization and CGRP release, mitochondrial dysfunction with oxidative stress, and systemic and neurogenic inflammation." (PMID 40426647, 2025). "In 2007, through a case–control design, we evaluated insulin and glucose dynamics in patients with migraine, individuals with other types of headache, and headache-free controls." (PMID 40426647, 2025). "For patients who suffer from migraine, a profile of greater glycemic stability appears to bring greater benefits, also improving insulin sensitivity." (PMID 39861467, 2025). "Some studies have shown that migraine patients exhibit impaired insulin sensitivity and elevated insulin levels, suggesting a possible role of the insulin receptor in migraine pathogenesis." (PMID 38347465, 2024). "Out of the nine glycemic traits, significant genetic correlation was observed for fasting insulin (FI) and glycated haemoglobin (HbA1c) with both migraine and headache, while 2-h glucose was genetically correlated only with migraine." (PMID 36808568, 2023). "Since CGRP antagonism has shown promising results at improving glucose and insulin metabolism in vivo, it would be important to probe putative benefits in metabolism in patients with migraine." (PMID 36175833, 2022). "In a study examining the effects of insulin, glucagon, and leptin in a rat model of migraine, changes in the transmission of trigeminal nociceptive inputs were identified, which provides insight into the dysregulated glucose state associated with migraines." (PMID 36248663, 2022). "Insulin has become a hormone of interest in migraine since numerous studies have identified insulin resistance in patients." (PMID 36175833, 2022). "These preliminary findings demonstrate a potential aberrant glucose metabolism in migraine patients, and are in line with reports about increased insulin levels in migraine patients." (PMID 35889884, 2022). "Two investigations have found that insulin sensitivity is reduced in patients with migraines, suggesting a role for insulin resistance in migraine and vascular disease comorbidity." (PMID 35627115, 2022). "Early experimental research suggests that the metabolic alterations produced by fasting or glucose or insulin administration can precipitate migraine attacks." (PMID 35627115, 2022). "Publications on migraine and fasting glucose, migraine and fasting insulin, and migraine and T2D were identified from a PubMed and Google Scholar database search and reviewed for this article." (PMID 35627115, 2022). "It is becoming apparent that the metabolism of insulin and glucose in migraine patients are affected and can play a pathophysiological function." (PMID 35627115, 2022). "Enhanced release of CGRP seems to be a crucial pathophysiological process involved in migraine and hyperinsulinemia coupled with decreased insulin sensitivity are long-term conditions facilitating migraine attacks." (PMID 35033025, 2022). "It has been suggested that outside attacks, migraine patients have an impaired insulin sensitivity and higher fasting plasma insulin levels compared to controls." (PMID 34819016, 2021). "Glucose levels and insulin metabolism, as well as mitochondrial dysfunction have been known to play a role in migraine pathology." (PMID 34819016, 2021).
migraine (continued). "In fact, the therapeutic action of the diet is not only due to the role played by ketones, but also to the change in the macronutrients consumed (see LGIT diet) and the correction of insulin resistance typical of migraine sufferers." (PMID 34371817, 2021). "Plasma glucose and insulin levels increase during spontaneous migraine attacks, leading to impairment in complex metabolic patterns." (PMID 33958992, 2021). "Regarding vaccine delivery, insulin delivery, and migraine treatment, MNs showed similar or more effective results than control groups." (PMID 33228098, 2020). "Several studies support insulin sensitivity alteration in migraine, that results in increasing glucose concentration." (PMID 32231773, 2019). "The findings indicate that a wide range of central genes is involved in migraine, but insulin is a key agent which significantly affects migraine patients." (PMID 32231773, 2019). "The findings of this study showed that metabolism control, especially insulin regulation, plays a critical role in migraine." (PMID 32231773, 2019). "We suggest that July, August 2019, insulin be evaluated in more details as a candidate for migraine biomarker." (PMID 32231773, 2019). "One serious AE (i.e., migraine) was reported in the NPH insulin group that was moderate in severity and was considered unlikely to be related to the trial product." (PMID 30014302, 2018). "For example, a recent study indicated that insulin sensitivity is impaired in patients with migraine, and another research confirmed an important relation between insulin resistance and migraine in sixty non-obese patients with migraine." (PMID 27617234, 2015). "The levels of 4-hydroxy-2-nonenal (HNE), increased in female patients compared to controls (OR for migraine of 4.55), were significantly correlated with the nitric oxide pathway, insulin- and lipid-metabolism." (PMID 23565964, 2013). "The patients with migraine have significantly higher level of fasting glucose and insulin; both of which remain elevated after glucose loading suggesting insulin resistance." (PMID 22278639, 2012). "Insulin sensitivity is significantly altered in migraine patients as measured by ISI-Stumvoll and OGIS-180 index." (PMID 22278639, 2012). "Furthermore, a recent study revealed significant genetic correlations between fasting insulin, glycosylated hemoglobin, and migraine, offering new insights into its pathogenesis at the genomic level." (PMID 40242623, 2025). "This supports the hypothesis that insulin dysregulation plays a pivotal role in migraine pathogenesis." (PMID 40426647, 2025). "Insulin resistance may be a critical metabolic link between migraine and its comorbidities, as insulin regulates mitochondrial signaling pathways." (PMID 40242623, 2025). "Personalized treatment approaches for migraine could benefit from biomarker-driven strategies: insulin and glucose markers, oxidative stress biomarkers, and genetic associations." (PMID 40426647, 2025). "This review highlights a potential missing link between migraine and AD: brain insulin resistance." (PMID 38913047, 2024). "Peptides such as insulin, glucagon, and leptin, which are involved in blood glucose and appetite regulation, could influence the neurobiology of migraines." (PMID 39452037, 2024). "Similarly to that observed in migraine, there is a strong link between insulin resistance and neuroinflammation in the pathophysiology of AD." (PMID 38913047, 2024). "In migraine-affected women, increased fasting neuropeptide Y levels in migraine may be a factor leading to increased insulin resistance due to specific alterations in energy intake and sympathetic–adrenal system activation." (PMID 37886939, 2023). "Furthermore, in addition to playing a significant role in maintaining normal brain function, insulin imbalances also raise the chance of developing migraines and other neurodegenerative diseases like Alzheimer’s and cognitive aging." (PMID 36808568, 2023).